MPO (myeloperoxidase)
Diseases named in the same sentence as MPO in open-access papers (continued):
Sharing a sentence is not in itself a finding about the gene and the disease.
asthma (85 papers, 2009 to 2026). "EGPA is a rare eosinophil-associated vasculitis characterized by asthma and eosinophilia, with MPO-ANCA positivity observed in a subset of patients." (PMID 41210913, 2026). "Asthma patients carrying the G allele at −1508A>G had significantly higher serum levels of periostin, myeloperoxidase, and urinary levels of 15-hydroxyeicosatetraenoic acid and sphingosine-1-phosphate (P = 0.016, P = 0.027, P = 0.032, and P = 0.010, resp)." (PMID 28659663, 2017). "This was the case for the MPO gene (rs2333227) that was previously associated with asthma in gene-environment interactions studies." (PMID 23066387, 2012). "Among the cytokines examined, asthma patients carrying the −1508G allele showed significantly higher serum MPO levels (150.91 ± 94.13 versus 108.26 ± 79.5 mg/L, P = 0.027) and serum periostin level than those of noncarrier asthma patients (91.83 ± 50.85 versus 71.07 ± 33.62 ng/mL, P = 0.016)." (PMID 28659663, 2017). "A polymorphism of the MPO gene was proposed to be associated with asthma susceptibility." (PMID 28659663, 2017). "Unlike the NHV group, the NAP group was likely unable to counteract ROS generation due to asthma-mediated inflammation and concomitant oxidative stress, demonstrated by increased MPO activity and susceptibility to lipid oxidation, in addition to reduced PON activity." (PMID 19563660, 2009). "In other inflammatory conditions, such as asthma, there seems to be an association between levels of MPO and iron, and it is suggested they may act in a concerted manner in the pathogenesis of the disease." (PMID 19549340, 2009). "To better understand the association between neutrophils and childhood asthma, we characterized the expression of MPO and HNL/NGAL levels in pediatric patients with asthma and investigated whether those could reflect airway inflammation and pulmonary function in childhood asthma." (PMID 39448961, 2024). "Myeloperoxidase (MPO) is an enzyme primarily produced by polymorphonuclear neutrophils and is typically released in response to infection, although dysregulated release is implicated in various disease processes, including asthma, cystic fibrosis, and other pulmonary pathologies." (PMID 39444041, 2024). "Thus, IL-8 and myeloperoxidase secreted in the airway after RV infection may be associated with the onset of asthma exacerbation." (PMID 22966430, 2012). "Taken together, our study revealed a significant upregulation of SCF expression in patients with asthma, which correlated with the expressions of IL-17A and MPO." (PMID 40674143, 2025). "Some outcomes are more acknowledged, such as EDN and ECP in asthma and the correlation between MPO and NGAL in heart disease." (PMID 40940435, 2025). "In patients with asthma, sputum MPO and HNL/NGAL levels showed a positive correlation with sputum neutrophil counts (MPO, r = 0.433, p < 0.001; HNL/NGAL, r = 0.584, p < 0.001) and with each other (r = 0.628, p < 0.001)." (PMID 39448961, 2024). "In patients with asthma, sputum MPO levels exhibited positive correlation with sputum neutrophils count (r = 0.433 p < 0.001)." (PMID 39448961, 2024). "EGPA consensus working group released the recommendations for patient assessment and management of EGPA in 2015, showing that positive MPO-ANCA is highly suggested for EGPA in the clinical context of asthma and eosinophils." (PMID 39312300, 2024). "Sputum MPO level was significantly higher in patients with asthma than in controls (194.3 [47.5–591.1] vs. 126.8 [24.3–290.8] ng/mL, p = 0.021)." (PMID 39448961, 2024). "Our study advances the understanding of neutrophilic inflammation in childhood asthma, proposing MPO and HNL/NGAL as potential markers for assessing asthma severity." (PMID 39448961, 2024). "In children and adults with severe asthma, blood or sputum MPO is increased, reflecting elevated neutrophil activity." (PMID 37569455, 2023).
asthma (continued). "Circulating levels and sputum concentrations of MPO were increased in patients with asthma compared to healthy individuals and correlated with extracellular DNA, a putative NET biomarker." (PMID 36359917, 2022). "Second, we measured MPO-DNA complexes by ELISA and found significantly higher levels of MPO-DNA in BALF supernatants of horses suffering from severe asthma as compared to those suffering from moderate asthma and to healthy controls." (PMID 35911691, 2022). "For moderate equine asthma, cf DNA showed the best area under the curve (AUC) of 0.5110, whereas AUC curve for MPO-DNA complexes and NETs areas were 0.3613 and 0.3269, respectively." (PMID 35911691, 2022). "A recent study demonstrated that sputum concentrations of MPO are increased in patients with asthma and correlated with a NET-derived biomarker." (PMID 34342773, 2022). "Conversely, for severe equine asthma, NETs evaluated by MPO-DNA ELISA showed the best AUC of 0.9060, followed by cf DNA (0.7575) and NETs areas (0.7115)." (PMID 35911691, 2022). "Second, the percentage of asthma at baseline was relatively lower in our cohort, and the ANCA-negative group had a higher proportion of asthma than the MPO-ANCA–positive group." (PMID 35833130, 2022). "Using immunofluorescence microscopy, we observed amorphous and unshaped structures colocalized with citH3 and MPO in severe asthma mouse lungs." (PMID 35958610, 2022). "In this study, we found that serum ECP and MPO levels were increased in patients with severe asthma compared to those with asthma and HCs, as well as in asthma patients compared to HCs." (PMID 34692717, 2021). "In this study, we found that serum MBD2, ECP and MPO levels and the percentage of Th2 cells in the peripheral blood was higher in patients with asthma and in those with T2 severe asthma." (PMID 34692717, 2021). "Serum MBD2 and MPO levels were higher in patients with Th17 severe asthma compared to patients with T2 severe asthma (P < 0.001), but serum ECP levels were lower in patients with Th17 severe asthma compared to those with T2 severe asthma (P = 0.003)." (PMID 34692717, 2021). "Serum MBD2, ECP and MPO levels were increased in patients with severe asthma compared to those with asthma (P < 0.001) and HCs (P < 0.001), as well as in patients with asthma compared to HCs (P < 0.001)." (PMID 34692717, 2021). "Serum MPO levels were higher in Th17 severe asthma than in T2 severe asthma, but serum ECP levels were lower in Th17 severe asthma than in T2 severe asthma." (PMID 34692717, 2021). "LPS-induced bronchial hyperreactivity, myeloperoxidase activity, frequency-decrease were significantly greater in Trpa1−/− mice." (PMID 32526913, 2020). "With the HLA region removed, ANCA-negative EGPA was more genetically similar to asthma than was MPO+ EGPA." (PMID 31719529, 2019). "Of the upregulated genes, NTS, TLR1, and MPO mRNA was only detectable in the asthma samples, whilst of the downregulated genes, IL7R and PDE4R mRNA were only observed in the control samples." (PMID 31221987, 2019). "Exposure to particulate matter induces airway inflammation in asthma, which is characterized by increased numbers of neutrophils and elevated interleukin-8 and myeloperoxidase levels." (PMID 26501307, 2015). "A 71-year-old Japanese man was diagnosed with EGPA based on his asthma, eosinophilia, lung opacity, refractory sinusitis, and positive myeloperoxidase-ANCA." (PMID 26559264, 2015). "The levels of IL-8 (CXCL8), a chemokine, and myeloperoxidase in nasal aspirates increase in children during RV infection-induced asthma exacerbation." (PMID 22966430, 2012). "We also plan to quantify other components of NETs, such as citrullinated histone H3 or myeloperoxidase, along with cfDNA, in airway samples to determine whether NETosis is the primary mechanism of increased cfDNA in airways of horses with severe asthma." (PMID 41375541, 2025).
asthma (continued). "We found that SCF expression was increased in the plasma, blood, and sputum samples from asthmatic patients and positively correlated to IL-17A and MPO expression, suggesting that SCF is associated with IL-17A production and neutrophilic inflammation during asthma." (PMID 40674143, 2025). "Finally, the quinoline Montelukast, approved for asthma and allergic rhinitis, decreases eosinophil cationic protein and IL-8 serum and sputum levels, as well as the sputum levels of myeloperoxidase, in CF patients." (PMID 40298549, 2025). "Our findings reveal that asthma promotes hypoxemia, leukocytosis, and pulmonary myeloperoxidase (MPO) activity by increasing lipid peroxidation, reactive oxygen and nitrogen species, inflammation associated with Th2 response, and airway remodeling in the lungs." (PMID 39000141, 2024). "Interestingly, recent research has reported autoantibodies to eosinophil peroxidase (EPX), an enzyme closely related to myeloperoxidase, in severe asthma sputum." (PMID 37334358, 2023). "It is also recommended that other inflammatory pathways (such as NF-κB, MAP kinase, and MPO activity) through which pomegranate extract may improve lung function parameters in asthma should be investigated." (PMID 36330147, 2022). "Notably, high-resolution confocal microscopy indicated the presence of MPO/PAD4-positive neutrophils in the BAL cells of the severe asthma mice, indicating that recruited neutrophils are a cellular source of dsDNA and citH3 in severe asthmatic airways." (PMID 35958610, 2022). "MPO-DNA has been proposed as a circulating biomarker of NETs in severe asthma." (PMID 36359917, 2022). "MPO-DNA has been proposed as a circulating NET marker of severe asthma." (PMID 34342773, 2022). "The underlying key genes in asthma pathogenesis and those regulated by treatment including Adipoq, HMOX1, SPP1, Cyp2e1, TNC, MB, MPO, Col9a1, Ckmt2, and Erbb4 were taken as examples to illustrate the positions and relationships with other points and midline in the figure." (PMID 33531915, 2021). "Moreover, MBD2 was positively correlated with Th17 cells and MPO, which is of great significance for the clinical diagnosis and treatment of Th17 severe asthma." (PMID 34692717, 2021). "This provides evidence for genetic differences between the two subtypes outside the HLA region, and suggests that the aetiology of ANCA-negative EGPA may more closely resemble that of asthma than does MPO+ EGPA." (PMID 31719529, 2019). "As such, the levels of sputum MPO in COPD patients was higher than that in asthma patients." (PMID 24588870, 2014). "Interactions of maternal oxidative stress genes (GSTM1, GSTP1, CAT, and MPO) with maternal prenatal exposure to air pollutants or tobacco smoke may contribute to asthma or allergic airway responsiveness." (PMID 22272211, 2012). "In addition to higher levels of LPO and MPO, patients with asthma, cystic fibrosis, and chronic obstructive pulmonary disease display higher levels of free iron in their lung compared to normal subjects." (PMID 22132121, 2011). "For example, MPA is typically myeloperoxidase (MPO)-ANCA positive and lacks granulomatous inflammation, while eosinophilic GPA (EGPA) shows ANCA positivity in only around 30%-40% of cases (when positive, mostly MPO) and is associated with asthma and eosinophilia." (PMID 41426880, 2025). "Interestingly, ECP and MPO did not demonstrate a significant association with any of the asthma-associated clinical indices, except MPO which was positively associated with non-atopic asthma (OR = 3.06, 95% CI: 1.119–8.363, p < 0.05) (data not shown)." (PMID 35387066, 2021). "In addition, these five gene have also been associated with the occurrence of asthma in different exposure settings and oxidative stress-related genetic variants of CAT, SOD2 and MPO have been reported to modify the association of urine phthalate metabolites levels and pulmonary function." (PMID 28208751, 2017).
asthma (continued). "In this study, compared to sputum MPO level, sputum HNL/NGAL level demonstrated better ability to accurately reflect the presence of asthma and airway inflammation." (PMID 39448961, 2024). "The levels of MPO and HNL/NGAL, secreted from azurophilic and gelatinase neutrophilic granules, were increased in pediatric patients with asthma, especially in those with moderate-to-severe persistent asthma." (PMID 39448961, 2024). "In this sense, the NFκB must participate in the pro-resolving pathways induced by CPC treatment because, in the OVA-induced asthma model, there is a similar pattern of COX2, NOS2, and MPO expression, as well as the reduction of proinflammatory cytokines." (PMID 39000141, 2024). "Sputum MPO and HNL/NGAL levels, which reflect neutrophil activation in airways, were increased in pediatric patients with asthma." (PMID 39448961, 2024). "In this case, the patient has clinical features of asthma and increased eosinophilia combined with positive P-ANCA and MPO-ANCA, being highly suspected of EGPA." (PMID 39312300, 2024). "Compared to those with MPO-ANCA and ANCA-negative, patients with PR3-ANCA less frequently had asthma and peripheral neuropathy, while more frequently had skin symptoms, pulmonary nodules, and a lower median eosinophil count." (PMID 37215720, 2023). "Plasma levels of several biomarkers of neutrophils activation such as MPO, MMP-9 and CXCL8 were increased in asthma patients compared to healthy subjects." (PMID 34342773, 2022). "The recruitment of inflammatory cells such as eosinophils, neutrophils and lymphocytes into the lungs is an important feature of asthma and we observed the same in our model based on BAL analyses, immunohistology and MPO assays." (PMID 35733161, 2022). "The reduction in levels of MPO as well as MDA by STIG and STIG+DEX is a desirable influence in managing airway inflammation in steroid-resistant asthma." (PMID 36060927, 2022). "Different analytical methods (e.g., dsDNA, MPO-DNA, CitH3) for the measurement of NET markers in asthma were used by several groups." (PMID 34342773, 2022). "A variety of different analytical approaches (e.g., double-strand DNA (dsDNA), myeloperoxidase-DNA (MPO-DNA), and citrullinated histone H3 (CitH3)) have been used as a surrogate measurement of NETs in asthma." (PMID 36359917, 2022). "In BALB/c-OVA model of asthma, the HIF-1α antagonist YC-1 suppressed HIF-1α expression and lowered the transcript levels of IL-5, IL-13, myeloperoxidase, and NOS2." (PMID 35453294, 2022). "Putative surrogate NET biomarkers (e.g., double-strand DNA (dsDNA), myeloperoxidase-DNA (MPO-DNA), and citrullinated histone H3 (CitH3)) have been found in different sites/fluids of patients with asthma." (PMID 36359917, 2022). "Plasma concentrations of the neutrophil-derived mediators MPO, matrix metallopeptidase 9 (MMP-9) and CXCL8 were augmented in patients with asthma compared to healthy subjects, which suggests that PMNs are activated in vivo." (PMID 36359917, 2022). "EGPA occurs in patients with asthma and peripheral and tissue eosinophilia, and ~30% of the patients present antineutrophil cytoplasm antibodies (ANCA) mainly specific for myeloperoxidase (MPO)." (PMID 33718405, 2021). "Activated neutrophils are able to release human neutrophil elastase (HNE) and myeloperoxidase (MPO) that exacerbate and prolong asthma symptoms and contribute to the airway inflammation." (PMID 34804178, 2021). "We also confirmed that MBD2 levels are positively correlated with MPO and Th17 cells but negatively correlated with FEV1/ FVC, FEV1%predicted, Th2 cells and ECP in patients with severe asthma." (PMID 34692717, 2021). "In a mouse model of asthma, suppression of HIF‐1α with YC‐1 reduced expression of IL‐5, IL‐13, myeloperoxidase (MPO) and inducible nitric oxide synthase (iNOS), which alleviated asthma symptoms." (PMID 32633061, 2020).
asthma (continued). "For example, eosinophil peroxidase (EPO) and myeloperoxidase (MPO) levels are increased in the peripheral blood, induced sputum, and BAL fluid from patients with stable asthma." (PMID 29029603, 2017). "Myeloperoxidase activity, a marker of leucocyte infiltration into inflamed tissue, has previously been reported to significantly increase after OVA-induced asthma-like reaction in the lungs of sensitized guinea pigs." (PMID 24444146, 2014). "However, sputum MPO and HNL/NGAL levels were significantly higher in patients with asthma than in controls (p = 0.021 and p < 0.001, respectively), especially in patients with moderate-to-severe persistent asthma." (PMID 39448961, 2024). "When comparing sputum MPO and HNL/NGAL levels among the subgroups based on asthma severity, patients with moderate-to-severe persistent asthma showed significantly higher sputum MPO levels than those of patients with intermittent asthma (407.6 [57.8–1,085.0] vs. 43.5 [13.2–141.4 ng/mL], p < 0.001)." (PMID 39448961, 2024). "Additionally, sputum MPO and HNL/NGAL levels reflected pulmonary dysfunction in pediatric patients with asthma." (PMID 39448961, 2024). "In terms of the systemic manifestations, renal involvement occurred more frequently in the MPO-ANCA–positive group (80.0% vs. 35.5%, p < 0.0001), whereas cardiac lesions (38.7% vs. 12.0%, p = 0.01) and asthma (76.3% vs. 56.0%, p = 0.04) presented more commonly in the ANCA-negative group." (PMID 35833130, 2022). "Furthermore, MBD2 was positively correlated with MPO and Th17 cells but negatively correlated with ECP and Th2 cells in patients with severe asthma." (PMID 34692717, 2021). "Although MPO has not been extensively studied in asthma, these results suggest that MPO is likely to promote Th17 asthma." (PMID 34692717, 2021). "In light of the clinical and genetic differences identified between MPO+ and ANCA-negative EGPA, we tested whether one subset was more genetically similar to asthma than was the other (see the ‘Methods’ section)." (PMID 31719529, 2019). "MPO, which is a haemoprotein secreted during activation of neutrophils, was considered to stimulate the production of MDA and participate in neutrophilic airway inflammation in asthma." (PMID 29568538, 2018). "However, EGPA is associated with allergies, asthma, and nasal polyps, and the ANCA immunofluorescence pattern is typically perinuclear, with specificity for MPO rather than PR3-ANCA positivity, which is more characteristic of GPA." (PMID 41426880, 2025). "However, FOR811A was not able to reduce MPO activity in the asthmatic groups, suggesting that it is ineffective in reducing neutrophil-mediated inflammation in asthma." (PMID 40136501, 2025). "Notably, our study suggests that sputum MPO and HNL/NGAL could serve as robust assessment variables for asthma severity, providing valuable insights into the current state of neutrophilic inflammation in the airways." (PMID 39448961, 2024). "Moreover, sputum MPO and HNL/NGAL may serve as appropriate assessment indicators of asthma severity in pediatric patients." (PMID 39448961, 2024). "A similar view has been found in studies of childhood asthma, which suggest that serum MPO is not involved in the assessment of inflammatory processes in childhood asthma, and the measurement of serum MPO appears to have no role in assessing the involvement of neutrophils in asthma." (PMID 38131042, 2023). "MPO is a marker of neutrophil activity, and the correlation analysis suggested that MBD2 might be involved in the development of asthma by mediating the differentiation of Th17 cells, which secrete the cytokine IL-17A to chemotactic neutrophils into the airway and causing chronic inflammation." (PMID 34692717, 2021). "Of the 10 MPO-ANCAINCR patients who experienced a clinical relapse, 7 developed systemic manifestations (with or without concurrent asthma or rhinosinusitis), while 3 exhibited isolated asthma and/or rhinosinusitis without systemic involvement." (PMID 40959075, 2025).